MMP10 (matrix metallopeptidase 10)
Diseases named in the same sentence as MMP10 in open-access papers (continued):
Sharing a sentence is not in itself a finding about the gene and the disease.
tendinopathy (4 papers, 2013 to 2023). "In regard to the expression of metalloprotease-encoding genes, increased expression of MMP2, MMP14, MMP16, ADAMTS2, ADAMTS3 as well as downregulation of MMP10 has also been found in tendinopathy." (PMID 38001919, 2023). "The expression of the stromelysines MMP3 and MMP10 was significantly decreased in the tendinopathy and chronic rupture groups compared to the acute ruptured tendons." (PMID 29385715, 2018). "Additionally, the expression of MMP3 and MMP10, the stromelysines, which have an important regulatory function on other MMPs, was significantly decreased in the tendinopathy and chronic rupture groups compared to the acute ruptured tendons." (PMID 29385715, 2018). "However, MMP1, MMP13, MMP10, ADAMTS5, TIMP3, versican, aggrecan, biglycan, decorin, fibronectin, fibrillin and COMP showed an opposite response with strain compared to tendinopathy." (PMID 23830915, 2013).
tongue tumor (4 papers, 2017 to 2023). "Overall, of 208 tongue tumors we find MMP10 overexpression in 86% of node-positive tongue tumors (n = 79; p < 0.00001)." (PMID 36650344, 2023). "Our immunohistochemical and real-time PCR analysis of 208 tongue tumors show overexpression of Matrix Metalloproteinase, MMP10, in 86% of node-positive tongue tumors (n = 79; p < 0.00001)." (PMID 36650344, 2023). "Here, we validate that MMP10 overexpression in a cohort of 208 tongue tumor samples (including samples of sufficient quality from the N-zero clinical trial) is significantly correlated with nodal metastases." (PMID 36650344, 2023). "Next, we screened for the expression of metastasis pathway-related genes in 52 primary tongue tumors and correlated with MMP10 expression." (PMID 36650344, 2023). "We validate the association of Fusobacterium with the inflammatory markers IL1B, IL6 and IL8, miRNAs hsa-mir-451a, hsa-mir-675 and hsa-mir-486-1, and MMP10 in the tongue tumor samples." (PMID 35252868, 2022). "Next, we performed immunohistochemical based validation of MMP10 expression in 50 primary early stage paired normal tongue tumors." (PMID 28939077, 2017). "Firstly, our immunohistochemical and real-time PCR-based analysis of MMP10 in 208 tongue tumor samples (including 98 N-zero clinical trial samples and 110 fresh-frozen samples) suggests a significant overexpression of MMP10 in primary tongue tumors of node-positive patients (p < 0.00001)." (PMID 36650344, 2023). "Additionally, we screened for the expression of MMP10 transcripts by real-time PCR across 110 tongue tumor samples." (PMID 36650344, 2023). "In overall, statistically significant differences in immunohistochemical scores were observed in tumors as compared to adjacent normal tissues (P-value < 0.0001, unpaired student-t-test) and MMP10 protein was up-regulated in a large proportion of primary tongue tumors." (PMID 28939077, 2017). "About 48% of primary tongue tumors displayed strong or moderate immunostaining of MMP10 protein, whereas 62% tongue tumors showed weak or no staining." (PMID 28939077, 2017).
tuberculosis (4 papers, 2014 to 2025). A chronic, recurrent infection caused by the bacterium Mycobacterium tuberculosis. "In this longitudinal analysis of patients with tuberculosis receiving treatment, we found that concentrations of plasma MMP-1, MMP-8, MMP-10, and PIIINP decreased with effective tuberculosis treatment over 2 months." (PMID 35510939, 2022). "MMP-1, MMP-3, MMP-7, and MMP-10 gene expression was analyzed by quantitative RT-PCR in M. tuberculosis stimulated PBMCs from 16 TB-IRIS participants treated with prednisone therapy compared with 12 patients who were placebo treated over 4 weeks of prednisone versus placebo treatment." (PMID 24136296, 2014). "Our findings show that M. tuberculosis stimulation of PBMCs differentially increased the transcript levels for MMP-1, MMP-7, MMP-10, and TIMP-1 genes in paradoxical TB-IRIS participants in 24 h cultures (pcorr ≤ 0.05) compared with non-IRIS controls." (PMID 24136296, 2014). "Upon stimulation with M. tuberculosis for 6 h, several of the MMP transcripts including MMP-1, MMP-3, MMP-7, and MMP-10 (pcorr ≤ 0.05) increased in abundance in both TB-IRIS and non-IRIS patients when compared with those of unstimulated cultures." (PMID 24136296, 2014). "However, after 24 h of stimulation with M. tuberculosis, MMP-1, MMP-7, and MMP-10 transcripts were observed to be significantly higher in the PBMC cultures of TB-IRIS as compared with those of non-IRIS patients (pcorr = 0.02, pcorr = 0.05 and p = 0.01, respectively)." (PMID 24136296, 2014).
acute kidney injury (3 papers, 2021 to 2024). Sudden and sustained deterioration of the kidney function characterized by decreased glomerular filtration rate, increased serum creatinine or oliguria. "The expression of MMP-10 is induced in both acute kidney injury (AKI) and CKD." (PMID 38674390, 2024). "However, the role of MMP-10 in the pathogenesis of acute kidney injury (AKI) is unknown." (PMID 33436543, 2021).
adenoma (3 papers, 2003 to 2025). A neoplasm arising from the epithelium. "Pairwise analysis further emphasized this trend, with 89% of paired samples exhibiting higher MMP10 levels in adenomas (p = 0.00001)." (PMID 40699620, 2025). "The expression of MMP10, however, showed a highly significant decrease in adenocarcinomas (mean: 5.29) compared to adenomas (mean: 8.96, p = 0.0001)." (PMID 40699620, 2025). "Furthermore, senescence-associated ECM remodeling genes (MMP1, 9, and 10 and TIMP1 and 2) exhibited increased levels in adenomas in relation to their matched malignant tissues where MMP10 was high in most of the samples." (PMID 40699620, 2025). "In addition to MMP-7 expression, 60–65% of Min adenomas express MMP-2 and MMP-10 (stromelysin-2) and 50% express MMP-3 and MMP-13 (collagenase) with expression limited to the stroma surrounding the adenoma." (PMID 12778076, 2003).
cervical tumors (3 papers, 2014 to 2022). "The role of matrix metallopeptidase 10 (MMP10) in cancer progression and metastasis has been studied in various cancer types and significantly increased expression of MMP10 was indicated in the cancer of skin, colon, lung, cervical tumors, and others." (PMID 35163468, 2022).
chronic periodontitis (3 papers, 2019 to 2021). A chronic inflammatory process that affects the tissues that surround and support the teeth. "In the occurrence of periodontitis, MMP10 may increase the risk of periodontitis; its mechanism is consistent with the local inflammatory response." (PMID 31192258, 2019). "In addition to this, MMP-1, MMP-2, MMP-10, and MMP-12 were also observed to be significantly increased in patients with OSCC compared to healthy patients and patients with benign oral masses (OBM) and mild chronic periodontitis (CPD)." (PMID 33892690, 2021).
colon adenocarcinoma (3 papers, 2015 to 2020). "Differences in the expression pattern of MMP7, MMP10 and MMP12 in 78 serum specimens of patients with an adenocarcinoma of the colon and serum specimens of a healthy control group were assessed using Luminex-100 technologies." (PMID 27431388, 2016).
dental caries (3 papers, 2017 to 2022). The decay of a tooth, in which it becomes softened, discolored, and/or porous. "Even more, a preliminary analysis of GWAS data suggested that variation in MMP10 may increase the risk for dental caries, thus providing compelling evidence for further investigation." (PMID 28348596, 2017). "Investigating the genetic association of MMP-10, MMP-14, and MMP-16 with dental caries shows that MMP-16 SNP rs2046315 is associated with dental caries." (PMID 36012195, 2022). "Here we investigated 28 genetic variants spanning the MMP10, MMP14, and MMP16 genes to detect association with dental caries experience in 13 age- and race-stratified (n = 3,587) samples from 6 parent studies." (PMID 28348596, 2017). "We investigated 28 SNPS in or near three MMP genes (MMP10, MMP14, and MMP16) for evidence of association with dental caries experience in 13 race- and age-stratified samples from 6 independent studies (n = 3600)." (PMID 28348596, 2017).
diabetic retinopathy (3 papers, 2021 to 2023). "One such example is that MMP10 expression is elevated in diabetic retinopathy patients’ corneas and implicated in the abnormal wound repair response." (PMID 34381080, 2021). "Notably, topical treatment with the recombinant MMP-10 impairs the wound healing in DM rats, which reveal that targeting MMP-10 is a promising option to improve wound healing in diabetic retinopathy." (PMID 36875064, 2023). "In ocular vascular pathology, elevated vitreous concentrations of MMP10 have been described in patients with venous occlusions with ischaemic manifestations, and the plasma levels correlate with vascular complications in patients with diabetic retinopathy." (PMID 35884862, 2022).
glomerular disease (3 papers, 2014 to 2025). "As MMP-10 was also upregulated in AKI and glomerular diseases, we decided to focus our studies on this proteinase." (PMID 40382334, 2025). "We recently showed that MMP-10 exerts a beneficial role by facilitating tubular cell repair and regeneration after AKI, whereas induction of MMP-10 aggravates podocyte injury, proteinuria and glomerulosclerosis in glomerular disease." (PMID 40382334, 2025). "Since we have previously documented a role for biomechanical strain in the induction of MMPs and the acceleration of glomerular disease in Alport mice we assessed the effect of FAK inhibition by TAE226 on biomechanical stretch-mediated induction of MMP-10 and MMP-12." (PMID 24915008, 2014).
glomerulosclerosis (3 papers, 2011 to 2025). A hardening of the kidney glomerulus caused by scarring of the blood vessels. "The increased expression of MMP10 was found specifically in the podocytes of injured glomeruli, further causing proteinuria and glomerulosclerosis." (PMID 37006258, 2023).
hepatocellular carcinoma (3 papers, 2016 to 2025). A malignant tumor that arises from hepatocytes. "Although mice with genetic deletion to not display a clear metabolic phenotype, MMP-10 has been implicated in the development of hepatocellular carcinoma." (PMID 40342635, 2025).
Hyperglycemia (3 papers, 2015 to 2023). An increased concentration of glucose in the blood. "An experimental murine model was carried out, with the aim of studying the renal expression of Mmp10 and Timp1 during hyperglycaemia." (PMID 31913319, 2020). "In particular, rapid histone H3K9/K14 hyperacetylation is associated with enhanced expression of HMOX1 (heme oxygenase (decycling) 1), IL-8, and matrix metalloproteinase 10 (MMP-10) in HAECs exposed to hyperglycemia." (PMID 26015812, 2015). "Since FAK activation is at the beginning of the angiotensin II signalling pathway, we propose a possible link between MMP-10 and RAS in DKD, where angiotensin II, induced by hyperglycaemia, could stimulate FAK activation resulting in Mmp10 overexpression." (PMID 31913319, 2020).
Mild cognitive impairment (3 papers, 2023 to 2025). "Indeed, selected MMPs (MMP-2 and MMP-10) have recently been linked to conversion from mild cognitive impairment (MCI) to AD dementia." (PMID 37221606, 2023). "This could potentially be explained by the expression of MMP10 by microglial cells in the brain, as elevated MMP10 levels contribute to ongoing inflammatory responses leading to axonal damage, potentially leading to functional deficits such as cognitive impairment." (PMID 40866991, 2025).
Obesity (3 papers, 2020 to 2024). Accumulation of substantial excess body fat. "MMP10/stromelysin-2 does not appear to contribute significantly and directly to adipose tissue development and angiogenesis in a model of dietary-induced obesity." (PMID 37445827, 2023). "When the effect of obesity was studied, the expression of LAMB1, Serpine1, MMP14, MMP10 appeared to decrease but a general downward trend could be noted." (PMID 33505957, 2020).
Parkinson disease (3 papers, 2022 to 2023). A progressive degenerative disorder of the central nervous system characterized by loss of dopamine producing neurons in the substantia nigra and the presence of Lewy bodies in the substantia nigra and locus coeruleus. "Increased CSF MMP-10 levels have also been linked to disease progression in Parkinson’s disease, suggesting a more general role for MMP-10 in the progression of neurodegenerative disorders." (PMID 37221606, 2023).
renal carcinoma (3 papers, 2019 to 2022). A carcinoma arising from the epithelium of the renal parenchyma or the renal pelvis. "The high level of MMP10 in renal cancer patients was found to be associated with poor survival (p = 0.000284)." (PMID 30836712, 2019). "However, only MMP-10 from renal carcinoma in the G2 phase reached an actual activity similar to the control tissue." (PMID 36231910, 2022). "Moreover, the elevated content and decreased specific activity of stromelysin-2 in cancer tissue indicate that MMP-10 is mainly present in an inactive form in renal carcinoma." (PMID 36231910, 2022). "In that regard, MMP-10 is detrimental by promoting renal cancer cell invasion and progression." (PMID 33436543, 2021).
rheumatoid arthritis (3 papers, 2023 to 2024). A chronic, systemic autoimmune disorder characterized by inflammation in the synovial membranes and articular surfaces. "In joint inflammatory disease, synoviocytes expressed MMP1, MMP3, and MMP10 to increase their invasiveness to destruct the cartilage in rheumatoid arthritis." (PMID 37006258, 2023).
small cell lung carcinoma (3 papers, 2011 to 2020). Small cell lung cancer (SCLC) is a highly aggressive malignant neoplasm, accounting for 10-15% of lung cancer cases, characterized byrapid growth, and early metastasis. "Mmp10 expression is also elevated in CSCs isolated from human small cell lung cancer cell lines, suggesting that Mmp10 may also function in the maintenance of these CSCs." (PMID 22545096, 2012). "In this regard, it is interesting to note that Mmp10 expression has been observed to be elevated in tumor-initiating stem-like cells isolated from human small cell lung cancer cell lines, suggesting that Mmp10 may also function in the maintenance of these CSCs." (PMID 22022614, 2011). "GSEA analysis showed that the MMP1, MMP3, and MMP10 high-expression groups participated in tumor-related ECM receptor interaction, small cell lung cancer, and other pathways." (PMID 32636440, 2020).
Stroke (3 papers, 2014 to 2025). Sudden impairment of blood flow to a part of the brain due to occlusion or rupture of an artery to the brain. "The histological location of TAFI and MMP-10 in stroke thrombi still remains unknown, and their presence could determine thrombus stability and the response to thrombolytic therapy." (PMID 33692737, 2021). "Future investigations with larger sample sizes and greater event rates are essential to clarify the predictive value of MMP-10 and MMP-7 for specific outcomes such as MI, stroke, or death." (PMID 40563493, 2025). "In this study, we therefore collected thrombi retrieved from large vessel occlusion (LVO) stroke patients and subjected them to histological assessment of different hemostatic parameters with a specific focus on TAFI and MMP-10." (PMID 33692737, 2021). "In this study, we demonstrate the presence of MMP-10 and TAFI in all thrombi retrieved from LVO stroke patients at the interface between RBC and platelet-rich areas, matching leukocytes." (PMID 33692737, 2021). "Altogether, this study confirms that plasma MMP-10 might play a key role in cardiovascular diseases and therefore could be a potential biomarker for LVO stroke patients." (PMID 33692737, 2021). "Thrombus MMP-10 and TAFI content correlate independently of confounding factors, the local TAFI expression being significantly lower in patients who died within 3 months after stroke onset." (PMID 33692737, 2021).
systemic sclerosis (3 papers, 2020 to 2022). A chronic disorder, possibly autoimmune, marked by excessive production of collagen which results in hardening and thickening of body tissues. "In contrast, MMP-10 was found to be overexpressed in perivascular macrophages and pulmonary vascular cells from the remodeled walls in patients with systemic sclerosis-associated pulmonary hypertension." (PMID 34975336, 2022).
aortic stenosis (2 papers, 2022 to 2025). Aortic valve stenosis is a aortic valve disease caused by the incomplete opening of the aortic valve. "Circulating MMP-10 is overexpressed in the aortic valve of patients with aortic stenosis." (PMID 34975336, 2022).
Arthritis (2 papers, 2017 to 2022). Inflammation of a joint. "Similarly, MMP10 was linked to renal damage and tissue destruction in arthritis." (PMID 29026368, 2017). "MMP-10 is present in synovial fluid and joint tissues of arthritis patients and potentiates cartilage collagenolysis." (PMID 36124688, 2022). "Taken together, the effects of CX3CL1, MMP-10, and Flt3L can be diverse, and it may depend on the immunological context if a decrease or increase in their level is more favorable in arthritis." (PMID 36124688, 2022).
astrocytoma (2 papers, 2022 to 2024). "Similar results were obtained in astrocytomas: specifically, in the genes MMP3, MMP8, MMP10, TIMP2, and TIMP4." (PMID 38474106, 2024).
Bladder (2 papers, 2021 to 2025). "Furthermore, β-catenin activation reciprocally upregulated the expression of MMP-10, thereby perpetuating kidney damage by forming a vicious cycle." (PMID 40382334, 2025).
carotid atherosclerosis (2 papers, 2022 to 2024). A thickening and loss of elasticity of the walls of carotid arteries that occur with formation of atherosclerotic plaques. "Reduced matrix metalloproteinase-10 (MMP-10) levels indicate early-stage carotid atherosclerosis; the protein profiles that predict this condition differ from those associated with intima-media thickness (IMT) development, possibly reflecting distinct pathological causes." (PMID 39199360, 2024).
cholesteatoma (2 papers, 2012 to 2023). A pathologic process characterized by the proliferation of keratinizing squamous epithelium resulting in the accumulation of keratin and cells in the middle ear and/or mastoid. "From a survey of cholesteatoma literature utilising transcriptomics, MMP10 has been identified in 3 studies to be downregulated in cholesteatoma samples compared to the control tissues." (PMID 36920900, 2023). "Among the 811 up-regulated extramatrix protein genes, MMP1, MMP7, MMp9, MMP10 and MMP12 and their substrate Osteopontin (SPP1) were amplified and their expression was significantly higher in cholesteatoma than in external canal skin (logFC>10)." (PMID 23285167, 2012). "In cholesteatoma matrix metalloproteinases MMP1, MMP9, MMP10, and MMP12 were up-regulated." (PMID 23285167, 2012). "Interestingly, MMP10 and COL17A1 are identified by the functional enrichment and GO analysis to regulate the degradation of the ECM, perhaps indicating the ECM has an important role in cholesteatoma aetiology." (PMID 36920900, 2023). "Real-time PCR of PI3, SPRR1B, LCN2 (lipocalin 2), MMP1, MMP9, MMP10, MMP12, SPP1, GJB2, Bcl-xl (BCL2L1), cIAP2 (BIRC3), S100A7A (koebnerisin), S100A9, SERPINB3, CEACAM6, KRT6B and SERPINB4 revealed that the expression levels of these proteins were higher in cholesteatoma than in external canal skin." (PMID 23285167, 2012).
colonic dysplasia (2 papers, 2016 to 2023). "Moreover, MMP-10-deficient mice had a higher burden of inflammation-associated colonic dysplasia, suggesting that MMP-10 may protect against both colonic inflammation and CAC." (PMID 38288108, 2023).